GRIN1 (glutamate ionotropic receptor NMDA type subunit 1)
Description:
Component of N-methyl-D-aspartate (NMDA) receptors (NMDARs) that function as heterotetrameric, ligand-gated cation channels with high calcium permeability and voltage-dependent block by Mg(2+). NMDARs participate in synaptic plasticity for learning and memory formation by contributing to the long-term potentiation (LTP). Channel activation requires binding of the neurotransmitter L-glutamate to the GluN2 subunit, glycine or D-serine binding to the GluN1 subunit, plus membrane depolarization to eliminate channel inhibition by Mg(2+). NMDARs mediate simultaneously the potassium efflux and the influx of calcium and sodium (By similarity). Each GluN2 or GluN3 subunit confers differential attributes to channel properties, including activation, deactivation and desensitization kinetics, pH sensitivity, Ca2(+) permeability, and binding to allosteric modulators.
Synonyms: GluN1; NMD-R1; hNR1; NMDAR1; NR1; DEE101; MRD8; NDHMSD; NDHMSR; NMDA1
Tractability: Small molecule: an approved drug acts on it; a structure with a bound ligand is known; a high-quality ligand is known; it belongs to a druggable protein family. Antibody: UniProt places it where antibodies can reach, with high confidence; its Gene Ontology location is reachable by antibodies, with high confidence; UniProt predicts a signal peptide or a membrane-spanning region. PROTAC: its protein half-life has been measured; a small molecule that binds it is known. Other modalities: a drug acting on it is in phase 2 or 3 trials.
Target class: Ion channel; Ionotropic glutamate receptor; Ligand-gated ion channel; NMDA receptor
Safety:
Unwanted effects reported when the protein is acted on. In parentheses: how it was acted on, where the effect was seen, and who reports it.
neurotoxicity (Bowes et al. (2012): activation, central nervous system; Lynch et al. (2017): inhibition, acute dosing, central nervous system, cardiovascular)
psychosis (ClinPGx; Lynch et al. (2017): inhibition, chronic or acute dosing, central nervous system, cardiovascular)
ataxia (inhibition, acute dosing; central nervous system, cardiovascular; source: Lynch et al. (2017))
convulsions (activation, acute dosing; central nervous system, cardiovascular; source: Lynch et al. (2017))
decreased convulsions (inhibition, acute dosing; central nervous system, cardiovascular; source: Lynch et al. (2017))
decreased memory (inhibition, acute dosing; central nervous system, cardiovascular; source: Lynch et al. (2017))
decreased pain (inhibition, acute dosing; central nervous system, cardiovascular; source: Lynch et al. (2017))
delirium and disoriented behaviour (activation; central nervous system; source: Bowes et al. (2012))
dizziness (inhibition, acute dosing; central nervous system, cardiovascular; source: Lynch et al. (2017))
drug abuse/dependence (inhibition, acute dosing; central nervous system, cardiovascular; source: Lynch et al. (2017))
hallucinations (activation; central nervous system; source: Bowes et al. (2012))
impaired social interactions (inhibition, chronic dosing; central nervous system, cardiovascular; source: Lynch et al. (2017))
increased blood pressure (inhibition, acute dosing and activation, acute dosing; central nervous system, cardiovascular; source: Lynch et al. (2017))
increased heart rate (inhibition, acute dosing; central nervous system, cardiovascular; source: Lynch et al. (2017))
increased locomotor activity (inhibition, acute dosing; central nervous system, cardiovascular; source: Lynch et al. (2017))
increased then decreased heart rate (activation, acute dosing; central nervous system, cardiovascular; source: Lynch et al. (2017))
neurodegeneration (inhibition, chronic dosing; central nervous system, cardiovascular; source: Lynch et al. (2017))
pain (activation, acute dosing; central nervous system, cardiovascular; source: Lynch et al. (2017))
psychosis (schizophrenia-like) (activation; central nervous system; source: Bowes et al. (2012))
seizures (activation; central nervous system; source: Bowes et al. (2012))
stereotypy (inhibition, chronic dosing; central nervous system, cardiovascular; source: Lynch et al. (2017))
Gene: Protein-coding gene on chromosome 9 (137,138,346 to 137,168,756, forward strand). Ensembl gene ENSG00000176884.
Subcellular location: Cell membrane; Postsynaptic cell membrane; Postsynaptic density membrane; Synaptic cell membrane
Pathways (Reactome):
Neuronal System: Assembly and cell surface presentation of NMDA receptors; Long-term potentiation; Negative regulation of NMDA receptor-mediated neuronal transmission; Neurexins and neuroligins; Ras activation upon Ca2+ influx through NMDA receptor; Synaptic adhesion-like molecules; Unblocking of NMDA receptors, glutamate binding and activation
Developmental Biology: EPHB-mediated forward signaling
Signal Transduction: RAF/MAP kinase cascade
Gene Ontology:
Molecular function: calcium channel activity; glutamate binding; glutamate-gated calcium ion channel activity; glycine binding; ligand-gated sodium channel activity; NMDA glutamate receptor activity; protein binding; amyloid-beta binding; calcium ion binding; calmodulin binding; glycine-gated cation channel activity; protein-containing complex binding; transmitter-gated monoatomic ion channel activity; ligand-gated monoatomic ion channel activity; monoatomic ion channel activity; signaling receptor activity
Biological process: calcium ion transmembrane import into cytosol; calcium ion transmembrane transport; cellular response to amyloid-beta; ionotropic glutamate receptor signaling pathway; monoatomic cation transmembrane transport; monoatomic cation transport; regulation of membrane potential; response to ethanol; response to glycine; sodium ion transmembrane transport; brain development; calcium ion homeostasis; chemical synaptic transmission; excitatory chemical synaptic transmission; excitatory postsynaptic potential; positive regulation of calcium ion transport into cytosol; positive regulation of excitatory postsynaptic potential; positive regulation of reactive oxygen species biosynthetic process; positive regulation of synaptic transmission, glutamatergic; positive regulation of transcription by RNA polymerase II; propylene metabolic process; protein heterotetramerization; regulation of monoatomic cation transmembrane transport; regulation of neuronal synaptic plasticity; regulation of synaptic plasticity; and 3 more
Cellular component: dendrite; neurotransmitter receptor complex; NMDA selective glutamate receptor complex; plasma membrane; cell surface; cytoplasm; dendritic spine; endoplasmic reticulum membrane; excitatory synapse; neuron projection; postsynaptic density; postsynaptic density membrane; postsynaptic membrane; presynaptic membrane; synapse; synaptic cleft; synaptic membrane; synaptic vesicle; terminal bouton; membrane
Genetic constraint (gnomAD): Loss-of-function variants: 38 observed, 86.85 expected, observed/expected ratio (o/e) 0.44, 90% interval 0.34 to 0.57. The upper end of that interval is the gene's LOEUF score, 0.57, which puts it in group 2 of 6, group 1 being the genes least tolerant of losing a copy. Missense variants: 552 observed, 1,176.9 expected, observed/expected ratio (o/e) 0.47, 90% interval 0.44 to 0.5. Synonymous variants: 533 observed, 506.45 expected, observed/expected ratio (o/e) 1.05, 90% interval 0.98 to 1.13.
Gene-disease validity (ClinGen):
ClinGen rates the evidence that GRIN1 causes each of these diseases.
complex neurodevelopmental disorder (autosomal dominant; autosomal recessive): Definitive. A disorder that involves more than one phenotype associated with the central nervous system, including but not limited to intellectual disability, autism, and seizures (epilepsy).
Homologues: Orthologues: pig GRIN1 (99% identical), rat Grin1 (99% identical), mouse Grin1 (99% identical), macaque GRIN1 (96% identical), guinea pig GRIN1 (96% identical), chimpanzee GRIN1 (90% identical), tropical clawed frog grin1 (90% identical), zebrafish grin1b (85% identical), zebrafish grin1a (81% identical), Drosophila melanogaster Nmdar1 (47% identical), Caenorhabditis elegans nmr-1 (34% identical). Paralogues in human: GRIK2 (25% identical), GRIA1 (24% identical), GRIA4 (24% identical), GRIK1 (24% identical), GRIK5 (24% identical), GRIA2 (24% identical), GRIK4 (24% identical), GRIA3 (23% identical), GRIK3 (23% identical), GRID2 (22% identical), GRIN2A (22% identical), GRID1 (22% identical), and 5 more.
Diseases named in the same sentence as GRIN1 in open-access papers:
GRIN1 is named in the same sentence as 170 diseases in open-access papers, as found by Europe PMC text mining. Sharing a sentence is not in itself a finding about the gene and the disease. The quoted sentences say what the papers report.
schizophrenia (87 papers, 2010 to 2026). A major psychotic disorder characterized by abnormalities in the perception or expression of reality. "It has been shown that disturbances in the expression of the GRIN1 gene are associated with the development of early forms of epileptic encephalopathies, schizophrenia, and mental retardation." (PMID 38069426, 2023). "The Grin1KD mouse has been used as a model to study aspects of schizophrenia, autism spectrum disorder, and most recently as a general model for variants in Grin1 that cause GRIN disorder." (PMID 37349472, 2023). "In particular, early postnatal ablation of the obligate NMDAR subunit gene GRIN1 in GABAergic interneurons resembles global GRIN1 loss in the constellation of schizophrenia-like behavioral and neural circuit aberrations." (PMID 35328011, 2022). "Saadat M. N-methyl-D-aspartate receptor NR1 subunit gene (GRIN1)G1001C polymorphism and susceptibility to schizophrenia: a metaanalysis.EXCLI J. 2010;9:11-6." (PMID 35774364, 2022). "Associationbetween polymorphisms in the GRIN1 gene 5′ regulatory region and schizophrenia ina northern Han Chinese population and haplotype effect on protein expression in vitro." (PMID 35774364, 2022). "The authors investigated the association of four SNVs (rs4880213, rs11146020, rs6293, and rs10747050) and one microsatellite marker (rs11146020) of the GRIN1 gene with the risk of schizophrenia in the German population of European origin." (PMID 35328011, 2022). "Begni S., Moraschi S., Bignotti S., Fumagalli F., Rillosi L., Perez J., Gennarelli M. Associationbetween the G1001C polymorphism in the GRIN1 gene promoter region and schizophrenia.Biol." (PMID 35774364, 2022). "Gene association studies have identified Grin1 as a candidate gene for schizophrenia and there is a strong association between the G1001C polymorphism on the Grin1 gene promoter and schizophrenia." (PMID 32497066, 2020). "The role of GRIN1 in the etiology of schizophrenia remains uncertain, and genetic association studies of the GRIN1 gene and schizophrenia in the northern Chinese Han population are relatively deficient." (PMID 30704411, 2019). "We conducted a case-control study to investigate the association between GRIN1 and the risk of schizophrenia in a northern Chinese Han population using Sanger DNA sequencing." (PMID 30704411, 2019). "In the present study, we examined the association between the GRIN1 gene and the risk of schizophrenia in a northern Chinese Han population." (PMID 30704411, 2019). "Using Sanger DNA sequencing, we illustrated that rs11146020, rs138961287, and rs117783907 in the promoter region of the GRIN1 gene are associated with schizophrenia in a northern Chinese Han population." (PMID 30704411, 2019). "Mutations in GRIN2A can induce idiopathic focal epilepsy, while GRIN1 has been associated with schizophrenia susceptibility." (PMID 25339366, 2015). "Recently we found a positive association between G1001C polymorphism (rs11146020) in the promoter of GRIN1 and developing of schizophrenia." (PMID 27843994, 2015). "Grin1 is a candidate susceptibility gene for neuropsychiatric disorders, including schizophrenia, bipolar disorder, and attention deficit/hyperactivity disorder (ADHD)." (PMID 23688147, 2013). "The gene, GRIN1, codes for the NR1 NMDA receptor subunit and GRIN1 gene abnormalities are a key research interest as a susceptibility gene for schizophrenia." (PMID 23189055, 2012). "Notably, hypomorphic mutations in Grin1 (an obligate subunit of NMDARs) also result in schizophrenia-like behaviors in mice." (PMID 41022686, 2025). "Here, we further find that genes contributing to glutamate homeostasis, e.g. the mitochondrial glutamate carrier 1 gene, Slc25a22, as well as the schizophrenia risk gene Grin1, distinctly differentiate between high- and low-performers in mPFC-dependent reversal learning." (PMID 37419882, 2023).
schizophrenia (continued). "Particularly, early postnatal ablation of the obligate NMDAR subunit gene Grin1 in GABAergic interneurons resembles global Grin1-loss in their constellation of schizophrenia-like behavioral and neural circuit aberrations." (PMID 34630033, 2021). "However, impaired synchronous inhibition of pyramidal neurons by Grin1-deleted PV neurons appears to be a key mechanism underlying schizophrenia-like phenotypes." (PMID 32859995, 2020). "Variations in GRIN1 have been identified as a risk factor for schizophrenia and drug dependence, supporting the hypotheses of glutamatergic dysfunction in these disorders." (PMID 30519197, 2018). "However, most previous studies of SNP associations with schizophrenia only investigated one or two genes in NMDARs, particularly GRIN1, GRIN2A, and GRIN2B." (PMID 26819771, 2016). "Since up-regulation of 5-HT2ARs in pyramidal neurons has been proposed as a common neural mechanism that could predispose to psychosis, the Grin1 mutant mouse can be a suitable model for research into the pathophysiology of psychosis in schizophrenia and other types of psychotic disorders." (PMID 35459266, 2022). "In our “schizophrenia models” Nmdar1 (N-methyl-D-aspartate receptor 1), an orthologue of GRIN1 was either down- or up-regulated, while Dysbindin, an ortholog of DTNBP1 was down-regulated." (PMID 41507144, 2026). "Together, our results demonstrate that the reduced spine formation at the hotspot during adolescence, rather than the overpruning of spines, is a common phenotype between the two genetic schizophrenia models and adolescent Grin1 cKO (see also fig." (PMID 41533795, 2026). "Numerous studies have linked GRIN1 mutations to various neurodevelopmental disorders, including ASD, epilepsy, schizophrenia, and intellectual disability." (PMID 41009441, 2025). "Missense mutations in the GRIN1 gene, which encodes the GluN1 subunit of NMDAR targeting by glycine, have been associated with epileptic encephalopathy or schizophrenia." (PMID 40161576, 2025). "In our “schizophrenia models” Nmdar133–37 (N-methyl-D-aspartate receptor 1), an orthologue of GRIN1 was either down- or up-regulated, while Dysbindin38–41, an ortholog of DNTBP1 was down-regulated." (PMID 38343805, 2024). "A follow-up pre-clinical study found robust antipsychotic-like effects of UNC9975 and UNC9994 on phencyclidine (PCP) pharmacological and Grin1 knockdown (Grin1-KD) genetic models of schizophrenia." (PMID 39612588, 2024). "Of note, variants among the GRIN3A are considered to be more relevant to autism spectrum disorders or schizophrenia, while GRIN1, GRIN2A, GRIN2B, and GRIN2D are more epilepsy-related." (PMID 38075685, 2023). "Previously, common polymorphic variants from the promoter regions of GRIA1, GRIA3, GRIN1, or GRIN2A were associated with susceptibility to addiction, migraine, or schizophrenia." (PMID 34945722, 2021). "We demonstrated that GSK3β inhibition restores the in vivo cortical gamma oscillation and cognitive function in the mouse model of Grin1 hypofunction relevant to schizophrenia." (PMID 32859995, 2020). "Additional research will be needed to fully ascertain the role of GRIN1 in the etiology of schizophrenia." (PMID 30704411, 2019). "We conducted a case-control study to investigate the association between the GRIN1 gene, which encodes the NR1 subunit, and the risk of schizophrenia in a northern Chinese Han population using Sanger DNA sequencing." (PMID 30704411, 2019). "Reduced expression of the obligatory NMDAR subunit GluN1 (also known as NR1; encoded by GRIN1) and also of GluN2C (NR2C, encoded by GRIN2C) has been reported in post-mortem prefrontal cortex tissue of schizophrenia patients." (PMID 31824347, 2019). "Single nucleotide or dinucleotide-repeated polymorphisms of the NMDAR subunit genes, such as NR1 (GRIN1), NR2A (GRIN2A), and NR2B (GRIN2B), increase susceptibility to schizophrenia." (PMID 31417356, 2019).